SLC7A11 (solute carrier family 7 member 11)
Diseases named in the same sentence as SLC7A11 in open-access papers (continued):
Sharing a sentence is not in itself a finding about the gene and the disease.
oral cancer (3 papers, 2018 to 2024). "miR-375-3p inhibits the proliferation of oral cancer cells by downregulating SLC7A11, which is reversed by SLC7A11 overexpression." (PMID 38892270, 2024). "Our findings indicate that TFP significantly elevates the levels of lipid-derived reactive oxygen species (ROS) and induces ferroptotic cell death in oral cancer cells through pathways involving autophagy, the SLC7A11/GPX4 axis, and mitochondrial damage." (PMID 39664583, 2024). "In conclusion, this study provides evidence that TFP induces ferroptosis in oral cancer cells through a multifaceted mechanism that includes ROS elevation, autophagy, the inhibition of SLC7A11/GPX4 signaling and mitochondrial damage in order to achieve ferroptosis in oral cancer cells." (PMID 39664583, 2024). "Recent studies demonstrated that smoking could induce the expression of xCT (SLC7A11) in oral cancer cells, suggesting that overexpression of xCT may support lung tumor progression." (PMID 29789716, 2018). "Treatment with TFP significantly upregulated the expression levels of pro-ferroptotic proteins, such as FTH1 and NCOA4, while downregulating the expression levels of proteins that reverse ferroptosis, such as SLC7A11, GPX4 and Nrf2, in oral cancer cells." (PMID 39664583, 2024). "Piperlongumine shows the antiproliferation of oral cancer cells by downregulating ferroptosis-inhibiting genes (FTH1, SLC7A11, and GPX4)." (PMID 38892270, 2024).
pancreatic adenocarcinoma (3 papers, 2016 to 2025). "SLC7A11 (solute carrier family 7 member 11) has recently been suggested as potential drug target in pancreatic adenocarcinoma." (PMID 35525914, 2022). "SLC7A11 is often aberrantly expressed in multiple cancer types, including pancreatic adenocarcinoma (PAAD) which implies that the regulation of tumor cell growth may be accomplished through the upregulation of SLC7A11 to cause disulfide death." (PMID 40299524, 2025).
polycystic ovary syndrome (3 papers, 2023 to 2025). A disorder that manifests as multiple cysts on the ovaries. "The circRHBG-miR-515-5p-SLC7A11 molecular axis, which is often upregulated in patients with polycystic ovary syndrome (PCOS), inhibits ferroptosis in granulosa cells." (PMID 38509545, 2024).
preeclampsia (3 papers, 2022 to 2023). Preeclampsia is a hypertensive disorder of pregnancy that is characterized by new-onset hypertension with proteinuria presenting after 20 weeks of gestation, and depending on mild or severe forms may initially present with severe headache, visual disturbances, and hyperreflexia. "MiR-30b-5p directly binds to SLC7A11 mRNA and represses its levels to induce the ferroptosis of trophoblasts under hypoxic conditions, leading to preeclampsia." (PMID 37686142, 2023). "It was also reported that miR-30b-5p reduces Pax3 levels to transcriptionally repress the expression of SLC7A11 to promote the hypoxia-induced ferroptosis of trophoblasts during preeclampsia." (PMID 37686142, 2023). "It was also found that the hypoxia (1% O2) increased miR-30b-5p to repress SLC7A11 and Pax3 (a transcription factor that promotes the expression of SLC7A11 and the iron exporter FPN1) levels, to induce ferroptosis of trophoblasts, leading to preeclampsia." (PMID 37048123, 2023).
pulmonary fibrosis (3 papers, 2024 to 2025). Chronic progressive interstitial lung disorder characterized by the replacement of the lung tissue by connective tissue, leading to progressive dyspnea, respiratory failure, or right heart failure. "The markers GPX4 and SLC7A11, which typically decrease during ferroptosis activation, were found significantly reduced in pulmonary fibrosis mice (P < 0.01)." (PMID 38584671, 2024). "Interestingly, APD downregulates ACSL4, PTGS2, and ROS while upregulating GPX4 and SLC7A11, indicating its role in inhibiting ferroptosis in pulmonary fibrosis." (PMID 38584671, 2024). "Furthermore, tuberostemonine enhances solute carrier family 7 member 11 (SLC7A11)/glutamate transporter expression, inhibits ferroptosis, and reduces inflammation and collagen deposition in the lung, thereby reducing pulmonary fibrosis." (PMID 39465434, 2024).
squamous cell carcinoma (3 papers, 2019 to 2025). A carcinoma arising from squamous epithelial cells.
Aortic dissection (2 papers, 2024). Aortic dissection refers to a tear in the intimal layer of the aorta causing a separation between the intima and the medial layers of the aorta. "METTL3 promotes ferroptosis of VSMCs by downregulating key ferroptosis regulatory proteins, solute carrier family 7 member 11 (SLC7A11) and ferroptosis suppressor protein 1 (FSP1); while the specific inhibitor of ferroptosis can alleviate the development and rupture of aortic dissection in vivo." (PMID 37815911, 2024).
choroidal neovascularization (2 papers, 2021 to 2022). An eye disorder described by the growth of new blood vessels that originate from the choroid through a break in the Bruch membrane into the sub–retinal pigment epithelium (sub-RPE) or subretinal space. "In our study, we assessed the role of SLC7A11 in laser-induced choroidal neovascularization (CNV) and explored the underlying mechanism." (PMID 33681224, 2021). "A rodent model of choroidal neovascularization (CNV) was established to determine the protein expression level of SLC7A11, a regulator of ferroptosis, and VEGF during disease progression and assessed the role of SLC7A11 in laser-induced CNV model." (PMID 35495915, 2022).
diabetic retinopathy (2 papers, 2024 to 2025). "We performed bioinformatic analysis using public database data, which revealed the potential roles of MYC and SLC7A11 in diabetic retinopathy (DR)." (PMID 39634176, 2024). "This approach will allow us to observe their effects on mitochondrial function and cell apoptosis, providing a more comprehensive understanding of the roles of MYC and SLC7A11 in diabetic retinopathy and offering scientific evidence for disease prevention and treatment." (PMID 39634176, 2024).
dry eye (2 papers, 2024 to 2025). "In the present study, we established a dry eye model in vitro and in vivo to elucidate whether AST inhibits ferroptosis via regulating SLC7A11/GPX4 and activates autophagy to protect against DED." (PMID 39224780, 2024). "In addition, in a dry eye mouse model, AST upregulated SLC7A11 and GPX4 and inhibited ferroptosis." (PMID 39224780, 2024).
endometritis (2 papers, 2024 to 2025). An acute or chronic, usually bacterial infectious process affecting the endometrium. "In this study, we found that ferroptosis is involved in the development of endometritis, and PU significantly inhibits the reduction of expression of ferroptosis‐related proteins GPX4 and SLC7A11 induced by S. aureus." (PMID 39042561, 2024).
epileptic seizures (2 papers, 2020 to 2026). "Other identified ferroptosis targets including SLC7A11 (ANOVA, F = 10.68, p < 0.001), 5-LOX (ANOVA, F = 23.53, p < 0.001) and ACSL4 (ANOVA, F = 4.521, p = 0.008) were slightly or hardly affected in KA-induced epileptic seizures when treatment with lapatinib." (PMID 33362556, 2020).
gastric tumor (2 papers, 2021 to 2023). "The expression of GPX4, NRF2, and SLC7A11 in GC was higher than that in normal tissues and varied in different stages of gastric tumor." (PMID 37768308, 2023).
hyperhomocysteinemia (2 papers, 2025). A serious metabolic condition caused by mutations in the MTHFR gene, medications, or nutritional deficiency. "In contrast, β-catenin overexpression antagonized the effects of hyperhomocysteinemia by upregulating SLC7A11 expression and downregulating ACSL4 expression." (PMID 40768425, 2025). "Hyperhomocysteinemia decreased the expression level of SLC7A11 while concurrently upregulating ACSL4 expression." (PMID 40768425, 2025).
hyperthyroidism (2 papers, 2025). Overactivity of the thyroid gland resulting in overproduction of thyroid hormone and increased metabolic rate. "To validate this hypothesis, we examined the expression levels of key genes related to glutathione metabolism, namely Slc7a11, Gsr, and Gclm, in single‐cell data from hyperthyroidism and wounded skin." (PMID 40558382, 2025).
hyperuricemia (2 papers, 2021 to 2025). An abnormally high level of uric acid. "SLC7A11 had lower expression in the intestine of mice with hyperuricemia (log2 fold change: −1.34, FDR = 2.9E–2)." (PMID 34887389, 2021).
intervertebral disc degeneration (2 papers, 2025). "These strategies provide potential therapeutic targets for delaying intervertebral disc degeneration by precisely inhibiting disulfidptosis signals, such as developing SLC7A11 inhibitors or GLUT agonists to maintain redox homeostasis in nucleus pulposus cells." (PMID 41229417, 2025). "In the targeted therapeutic strategies for disulfidptosis in intervertebral disc degeneration (IVDD), research focuses on regulating SLC7A11-mediated redox imbalance to maintain cellular homeostasis." (PMID 41229417, 2025).
intracerebral hemorrhage (2 papers, 2024 to 2025). A cerebrovascular disorder characterized by bleeding into one or both cerebral hemispheres including the basal ganglia and the cerebral cortex. "The potential antioxidant agent crocin has been shown to inhibit neuronal cell ferroptosis through the expression of Nrf2 and SLC7A11, thereby alleviating intracerebral hemorrhages." (PMID 38396952, 2024).
iron deficiency (2 papers, 2022 to 2024). "Among the downstream targets of NRF2, GPX4 and SLC7A11 are important markers of iron deficiency anemia." (PMID 38693581, 2024).
iron metabolism disorder (2 papers, 2022 to 2024). "Mechanically, ferroptosis is associated with iron metabolism disorder, lipid peroxidation accumulation, and glutathione (GSH) and solute carrier family 7 member 11 (SLC7A11) deficiency." (PMID 39512823, 2024). "Mechanically, ferroptosis is associated iron metabolism disorder, lipid peroxidation accumulation, glutathione (GSH) and solute carrier family 7 member 11 (SLC7A11) deficiency." (PMID 34811833, 2022).
iron overload (2 papers, 2023 to 2026). "In a mouse model of cardiac iron overload obtained by cardiac myocyte-specific deletion of the ferritin H gene, cardiac overexpression of Slc7a11 prevented ferroptosis by increasing glutathione levels." (PMID 37930434, 2023).
kidney stone (2 papers, 2023 to 2024). "Western blot analysis showed decreased expression of SLC7A11 and GPX4, which are key proteins in the regulation of ferroptosis, and increased expression of the fibrosis-related proteins fibronectin and α-SMA in mice with CaOx kidney stones, with a more pronounced effect over time." (PMID 37893066, 2023).
lentivirus infection (2 papers, 2023 to 2024). Virus diseases caused by the Lentivirus genus. "To further functionally test the role of the 4EBP1/SLC7A11 axis in regulating ferroptosis caused by MK2206 and trametinib, we first overexpressed SLC7A11 in A2780R by lentivirus infection." (PMID 38842940, 2024). "To examine the role of SLC7A11 in VD-induced ferroptosis of CCSCs, we used lentivirus infection to overexpress SLC7A11 transcripts and shRNA (sh#2) to silence SLC7A11 and then performed VD intervention concomitantly." (PMID 36846715, 2023).
lung diseases (2 papers, 2021 to 2024). "Specifically, high expression of SLC7A11 and GPX4 is a potential target for the treatment of lung diseases." (PMID 38562175, 2024).
lupus (2 papers, 2023 to 2024). "Considering B cells in the lupus kidney exhibited higher expression of SLC7A11, a downstreaming molecule mediated by the IL-6 in mediating ferroptosis resistance." (PMID 37273451, 2023). "Additionally, neutrophils in lupus-afflicted kidneys supplied IL-6 via SLC7A11 to boost B cell resistance against ferroptosis; suppressing SLC7A11 markedly heightened B cell ferroptosis while reducing B cell proliferation." (PMID 38965216, 2024).
malaria (2 papers, 2023 to 2025). Malaria is a serious and sometimes fatal disease caused by a parasite that commonly infects a certain type of mosquito which feeds on humans. "Heather S Kain discerned that impeding GPX4 or SLC7A11 precipitates a substantial reduction in malaria liver-stage parasite infection." (PMID 37840106, 2023). "Further, Erastin and Sorafenib, inhibitors of SLC7A11, exhibit inhibitory actions on malaria." (PMID 37840106, 2023). "Notably, Slc7a11 exhibits unique biological functions in malaria parasite liver‐stage infection regulation: targeted inhibition of GPX4 or SLC7A11 significantly suppresses parasite proliferation through enhanced LPO, whereas NOX1 (NADPH oxidase 1, NADPH1) and TFR1 blockade produces opposing effects." (PMID 40919133, 2025).
metastatic cancer (2 papers, 2023 to 2024). A carcinoma which has spread from the original site of growth to another anatomic site. "The expression levels of SLC7A11 and vimentin were higher in cancer tissues compared with normal tissues, especially the IRSs of SLC7A11 and vimentin were higher in metastatic cancer tissues than in non-metastatic cancer tissues." (PMID 39543094, 2024).
non‐alcoholic steatohepatitis (2 papers, 2025). "Also, SLC7A11 impaired NLRP3 inflammasome expression in nonalcoholic steatohepatitis advocating the involvement of ferroptosis in NLRP3 activation." (PMID 40622464, 2025).
oropharyngeal squamous cell carcinoma (2 papers, 2021 to 2024). "Indeed, we have been previously reported that the low expression of SLC7A11 predicted short OS as well as DFS in a smaller cohort of 489 OC patients; and low levels of VCP in HPV-negative patients was related to worse 5-year DFS in oropharyngeal squamous cell carcinoma." (PMID 34790572, 2021).
ovarian dysfunction (2 papers, 2023 to 2026). The inability of the ovaries to function. "Previous studies have reported a correlation between GSH, GPX4 and ovarian dysfunction; however, few studies have focused on the correlation between SLC7A11 and POI43–46." (PMID 36932163, 2023).
periodontitis (2 papers, 2023). An acute or chronic inflammatory process that affects the tissues that surround and support the teeth. "We found that the expression of SLC7A11 and GPX4 was suppressed in the periodontitis group, and curcumin significantly improved the expression of SLC7A11 and GPX4 verified by qPCR, Western blotting and IHC assay." (PMID 37372983, 2023). "The IHC staining demonstrated a significantly decreased GPX4 and SLC7A11 expression in the periodontitis and Cur 50 group compared with the control group and the other curcumin group." (PMID 37372983, 2023). "Inhibition of ferroptosis rescued the diabetic periodontitis condition-induced osteocyte cell death as well as diabetic periodontitis condition-inhibited expression of SLC7A11 and GPX4 in osteocytes." (PMID 37432277, 2023). "Osteocytes cultured in diabetic periodontitis conditions also showed downregulated SLC7A11 and GPX4 mRNA expression." (PMID 37432277, 2023). "Moreover, ligature-induced periodontitis in mice treated with curcumin exhibited increased expression levels of SLC7A11 and GPX4 and decreased expression levels of ACSL4 and TfR1." (PMID 37372983, 2023). "This suggested that curcumin may exert its protective effect on periodontitis by inhibiting ferroptosis via the SLC7A11/GPX4 axis." (PMID 37372983, 2023). "To further investigate the occurrence of ferroptosis in periodontitis, we tested the expression level of ferroptosis-markers such as ACSL4, SLC7A11, GPX4 and TfR1 in the gingival tissue." (PMID 37372983, 2023). "Diabetic periodontitis aggravated periodontitis pathogenicity and inhibited the expression of GPX4 and SLC7A11 in alveolar osteocytes and resveratrol alleviated these effects." (PMID 37432277, 2023). "Moreover, resveratrol also mitigated the periodontitis pathogenicity, restored the alveolar osteocyte number and morphology, and upregulated osteocytic expression of GPX4 and SLC7A11 in diabetic periodontitis mice." (PMID 37432277, 2023). "We have presented evidence suggesting that ferroptosis is involved in the development and progression of ligature-induced periodontitis, and curcumin attenuates ferroptosis by decreasing the ROS and MDA accumulation and reversing the down-regulation of GPX4 and SLC7A11." (PMID 37372983, 2023).
synovitis (2 papers, 2022 to 2024). Inflammation of a synovial membrane. "In a lipopolysaccharide-induced synovitis model in one report, an increase in iron content and TFRC, as well as a decrease in GPX4, SLC7A11 and SLC3A2, was described, leading to increased cell death." (PMID 39513899, 2024). "A paper in 2021 showed that the iron content and the expression of TfR1 and NCOA4 in synovitis cells increased, while the expression of GPX4, SLC7A11, SLC3A2L, and NRF2 decreased in LPS-induced synovitis cell model, resulting in increased synovitis cells death and decreased cell viability." (PMID 35958605, 2022).
Type II Diabetes (2 papers, 2023 to 2026). "Genes annotated to CpGs that were associated with type 2 diabetes included ABCA1, ABCG1, CPT1A, SREBF1, SLC7A11, SLC7A5, and TXNIP among others (see S12 Table for full details)." (PMID 37410739, 2023).
abscesses (1 paper, 2024). "Immunohistochemical staining confirmed the strikingly down-regulated expression of SLC7A11 in the area around abscess of infected femurs from Lyz2Cre-Slc7a11f/f mice." (PMID 38725861, 2024). "Double immunofluorescence staining also showed a significant increase in the number of Lyz2+SLC7A11+ cells around the abscesses in the bone marrow cavity." (PMID 38725861, 2024). "Here, in a mouse model of S. aureus osteomyelitis, we identified significantly up-regulated expression of SLC7A11 in both transcriptomes and translatomes of CD11b+F4/80+ macrophages, and validated a predominant distribution of SLC7A11 in F4/80+ cells around the S. aureus abscess." (PMID 38725861, 2024). "Interestingly, SLC7A11 exhibited a characteristic distribution around the abscess in bone marrow." (PMID 38725861, 2024).
acute lung injury (1 paper, 2021). A condition of lung damage that is characterized by bilateral pulmonary infiltrates (pulmonary edema) rich in neutrophils, and in the absence of clinical heart failure. "In addition, phosphorylated STAT3 could upregulate the expression of SLC7A11 and reduce ferroptosis, thereby improving the pathological processes associated with acute lung injury." (PMID 34692796, 2021).
adrenocortical adenoma (1 paper, 2025). "Accordingly, gene expression analysis indicated that EZH2 and SLC7A11 are upregulated in ACC in comparison to normal adrenal (NC) and adrenocortical adenoma (ACA)." (PMID 40229247, 2025).
alcoholic liver diseases (1 paper, 2022). A disorder caused by damage to the liver parenchyma due to alcohol consumption. "Nrf2 can inhibit ferroptosis in alcoholic liver disease by regulating SLC7A11 and HO-1, and specific knockout of the Nrf2 gene can reduce the expression of SLC7A11 and inhibit the activity of GPX, thus enhancing the sensitivity of PC12 cells to ferroptosis induced by erastin." (PMID 36225311, 2022).
allergic asthma (1 paper, 2025). A asthma with a basis in a pathological type I hypersensitivity reaction. "In house dust mite‐induced allergic asthma, increased production of ROS, depletion of glutathione (GSH), and downregulation of glutathione peroxidase 4 (GPX4) and solute carrier family 7 member 11 (SLC7A11) suggest the occurrence of ferroptosis during this process." (PMID 40667723, 2025).